DGAT2 (diacylglycerol O-acyltransferase 2)
Description:
Essential acyltransferase that catalyzes the terminal and only committed step in triacylglycerol synthesis by using diacylglycerol and fatty acyl CoA as substrates. Required for synthesis and storage of intracellular triglycerides. Probably plays a central role in cytosolic lipid accumulation. In liver, is primarily responsible for incorporating endogenously synthesized fatty acids into triglycerides (By similarity). Also functions as an acyl-CoA retinol acyltransferase (ARAT) (By similarity). Also able to use 1-monoalkylglycerol (1-MAkG) as an acyl acceptor for the synthesis of monoalkyl-monoacylglycerol (MAMAG).
Synonyms: ARAT; HMFN1045; GS1999FULL
Tractability: Small molecule: a high-quality ligand is known. Antibody: UniProt predicts a signal peptide or a membrane-spanning region. PROTAC: ubiquitination databases record sites on it; a small molecule that binds it is known.
Target class: Enzyme; Transferase
Chemical probes: PD084817, ervogastat (high quality)
Gene: Protein-coding gene on chromosome 11 (75,759,512 to 75,801,542, forward strand). Ensembl gene ENSG00000062282.
Subcellular location: Endoplasmic reticulum membrane; Lipid droplet; Cytoplasm, perinuclear region
Subcellular location (Human Protein Atlas): Cytosol; Vesicles
Pathways (Reactome):
Metabolism: Acyl chain remodeling of DAG and TAG; Triglyceride biosynthesis
Gene expression (Transcription): MLL4 and MLL3 complexes regulate expression of PPARG target genes in adipogenesis and hepatic steatosis
Gene Ontology:
Molecular function: diacylglycerol O-acyltransferase activity; protein binding; retinol O-fatty-acyltransferase activity; 2-acylglycerol O-acyltransferase activity; acyltransferase activity, transferring groups other than amino-acyl groups; protein homodimerization activity
Biological process: diacylglycerol metabolic process; long-chain fatty-acyl-CoA metabolic process; monoacylglycerol biosynthetic process; triglyceride biosynthetic process; cellular response to oleic acid; cholesterol homeostasis; diacylglycerol biosynthetic process; fat pad development; fatty acid homeostasis; intracellular triglyceride homeostasis; lipid storage; low-density lipoprotein particle clearance; regulation of plasma lipoprotein particle levels; negative regulation of fatty acid oxidation; positive regulation of gluconeogenesis; positive regulation of triglyceride biosynthetic process; regulation of cholesterol metabolic process; regulation of lipoprotein metabolic process; response to nutrient; retinol metabolic process
Cellular component: endoplasmic reticulum; endoplasmic reticulum membrane; lipid droplet; membrane; perinuclear endoplasmic reticulum membrane; mitochondrion; perinuclear region of cytoplasm
Genetic constraint (gnomAD): Loss-of-function variants: 33 observed, 47.43 expected, observed/expected ratio (o/e) 0.7, 90% interval 0.53 to 0.93. The upper end of that interval is the gene's LOEUF score, 0.93, which puts it in group 3 of 6, group 1 being the genes least tolerant of losing a copy. Missense variants: 446 observed, 486.83 expected, observed/expected ratio (o/e) 0.92, 90% interval 0.85 to 0.99. Synonymous variants: 191 observed, 187.68 expected, observed/expected ratio (o/e) 1.02, 90% interval 0.9 to 1.15.
Homologues: Orthologues: chimpanzee DGAT2 (100% identical), macaque DGAT2 (99% identical), mouse Dgat2 (95% identical), rat Dgat2 (95% identical), guinea pig DGAT2 (94% identical), dog DGAT2 (91% identical), tropical clawed frog dgat2 (72% identical), pig DGAT2 (71% identical), zebrafish dgat2 (64% identical), Caenorhabditis elegans Y53G8B.2 (37% identical), Caenorhabditis elegans dgtr-1 (36% identical), Caenorhabditis elegans K07B1.4 (35% identical), and 4 more. Paralogues in human: DGAT2L6 (45% identical), MOGAT3 (44% identical), MOGAT1 (43% identical), AWAT1 (43% identical), AWAT2 (41% identical), MOGAT2 (39% identical).
Diseases named in the same sentence as DGAT2 in open-access papers:
DGAT2 is named in the same sentence as 73 diseases in open-access papers, as found by Europe PMC text mining. Sharing a sentence is not in itself a finding about the gene and the disease. The quoted sentences say what the papers report.
Hepatic steatosis (66 papers, 2012 to 2025). Steatosis is a term used to denote lipid accumulation within hepatocytes. "Inhibiting diacylglycerol acetyltransferase (DGAT1, DGAT2) enzymes (iDGAT1, iDGAT2), involved in triglyceride (TG) synthesis, improves hepatic steatosis in metabolic dysfunction-associated steatotic liver disease (MASLD) patients." (PMID 39201759, 2024). "A recent study indicates that hepatic DGAT2 deficiency leads to a reduction of diet-induced hepatic steatosis, thus supporting the application of DGAT2 inhibitors as a therapeutic approach to ameliorate NAFLD and associated diseases." (PMID 33628193, 2021). "Further, DGAT2 deficiency using antisense oligo improved hepatic steatosis but exacerbated liver damage and hepatic fibrosis." (PMID 34681759, 2021). "Conversely, up-regulation of diacylglycerol O-acyltransferase 2 (DGAT2) resulted in increased hepatic steatosis and was associated with a significant increase in liver inflammatory markers." (PMID 27314342, 2016). "Furthermore, NPY deficiency ameliorated HFD-induced fatty liver by regulating genes involved in fatty acid uptake and Tg synthesis, including Cd36, Lpl, Dgat2, and Cyp4a14." (PMID 34829968, 2021). "As DGAT2 plays a critical role in the generation of TGs and high levels of TG are associated with several negative clinical outcomes, e.g., insulin resistance, hyperlipidemia, and fatty liver disease, the rationale was to block TG synthesis via pharmacologic modulation (lowering) of DGAT2 activity." (PMID 40281645, 2025). "Research conducted on obese mouse models has demonstrated that lowering DGAT2 expression through antisense oligonucleotide treatment improves hepatic steatosis, but simultaneously exacerbates the development of liver fibrosis (Schulze and McNiven 2023; 2019)." (PMID 41157845, 2025). "Specifically, genetic deletion or pharmacological DGAT1 and DGAT2 inhibition reduced hepatic steatosis and hypertriglyceridemia in murine models and MASLD patients (NCT01811472)." (PMID 39201759, 2024). "The enzymes DGAT1 and DGAT2, involved in the final step of triacylglycerol synthesis, also play a role in developing hepatic steatosis." (PMID 39275255, 2024). "A parallel study showed administrations of ASOs targeting DGAT2 in HFD-fed mice and ob/ob mice both efficiently reduced liver Dgat2, resulting in lowered intrahepatic TG level and attenuated hyperlipidemia, as well as reduction of hepatic steatosis." (PMID 38665220, 2024). "In studies of hepatic steatosis, mice over-expressing DGAT2, an enzyme that catalyzes the final step of hepatic triglyceride biosynthesis, was demonstrated to develop hepatic steatosis with normal plasma glucose and insulin levels and normal insulin tolerance." (PMID 39618812, 2024). "Ervogastat (PF-06865571), a novel, potent, and specific DGAT2 inhibitor, has shown safety and promise in reducing hepatic steatosis in early clinical trials (NCT03230383, NCT03513588)." (PMID 38500157, 2024). "It has been previously demonstrated that niacin improves hepatic steatosis by downregulating DGAT2 and reducing TG synthesis which, in turn, lead to a decreased oxidative stress." (PMID 36937355, 2023). "In the context of ALD, both Dgat1 and Dgat2 have been shown to be induced in the alcohol-exposed liver leading to hepatic steatosis." (PMID 35864895, 2022). "Inhibition of DGAT2 expression has been shown to improve insulin resistance and hepatic steatosis in T2DM rats, suggesting that DGAT2 plays an important role in hepatic steatosis and hypertriglyceridemia in T2DM." (PMID 36438823, 2022). "Genetically silencing DGAT2, an essential enzyme catalyzing the final step in hepatocyte TG biosynthesis, rescued hepatic steatosis, but aggravated liver injury." (PMID 36313120, 2022). "Researchers have observed improvements in hepatic steatosis with a marked reduction in liver triacylglycerol content with Dgat2-ASO administration in mice fed a high fat diet." (PMID 35295579, 2022).
Hepatic steatosis (continued). "In conclusion, KDM7A plays a pivotal role in the development of hepatic steatosis by upregulating DGAT2 expression." (PMID 34681759, 2021). "Two diacylglycerol acyltransferases (DGATs), namely, DGAT1 and DGAT2, are known to play an important role in hepatic TG synthesis and induce hepatic steatosis through the catalysis of the final step of TG synthesis." (PMID 34681759, 2021). "Taken together, these results indicate that KDM7A overexpression induces hepatic steatosis through upregulation of DGAT2 by erasing H3K9me2 and H3K27me2 on the promoter." (PMID 34681759, 2021). "Taken together, these results indicate that KDM7A upregulates the expression of DGAT2, thereby possibly playing a key role in the development of hepatic steatosis." (PMID 34681759, 2021). "DGAT2 antisense-treated mice and hepatic-specific DGAT2 knockout mice have lower TG accumulation and ameliorated hepatic steatosis." (PMID 34681759, 2021). "Together, these results indicate that KDM7A promotes DGAT2 expression, leading to increased intracellular TG accumulation, and consequently results in the development of hepatic steatosis." (PMID 34681759, 2021). "In summary, this study demonstrated that pharmacologic inhibition of the BMP signaling pathway prevented the development of hepatic steatosis in a murine model of NAFLD likely via SMAD-dependent regulation of Dgat2." (PMID 32561790, 2020). "Deacylglycerol acyltransferase 2 (DGAT2) catalyzes the de novo synthesis of triglycerols from newly synthesized FAs (CoA + triacylglycerol from acyl-CoA + 1,2-diacylglycerol), while hepatic overexpression of DGAT2 in mice leads to hepatic steatosis." (PMID 32947972, 2020). "Regarding lipid metabolism, we found that AAV-mediated IRA expression also ameliorated hepatic steatosis by decreasing the expression of Fasn, Pgc1a, Acaca and Dgat2 and increasing Scd-1 expression." (PMID 30642871, 2019). "The hepatic overexpression of Dgat2, which catalyzes the final step of triglyceride synthesis, led to hepatic steatosis in mice, and liver-specific disruption of Pparγ or Srebf1 protected mice against hepatic steatosis." (PMID 27213439, 2016). "DGAT2 is the rate-limiting enzyme in TG synthesis and plays an important role in the development of fatty liver diseases." (PMID 26868515, 2016). "The qRT-PCR measurements indicated that HFrD feeding promoted hepatic TG accumulation (hepatic steatosis) along with increased expression of lipogenic genes that contribute to hepatic steatosis such as Fasn, Acac1, Scd1, Gpat1 and Dgat2." (PMID 26394137, 2015). "Our data suggest that LJEE can prevent hepatic steatosis by reducing hepatic DGAT2 expression, as well as by inducing PPARα expression." (PMID 26506376, 2015). "Reduction of DGAT-2 expression by antisense oligonucleotide attenuates hepatic steatosis in high fat diet-induced obese mice and ob/ob mice, and in high fat diet-fed rats." (PMID 26031670, 2015). "Recent studies have demonstrated that DGAT-2 plays an important role in hepatocyte triglyceride synthesis, thereby contributing to hepatic steatosis." (PMID 26031670, 2015). "While suppression of DGAT2 with antisense oligonucleotide treatment improves hepatic steatosis in a diet induced NAFLD and obesity rat models." (PMID 26693162, 2015). "SBS possesses a repressive property on hepatic steatosis, which is associated with inhibition of SREBP1c, PPARγ, ACC, DGAT2, and FAS, and induction of PPARα, suggesting a potential application of SBS in treatment of HFD-induced NAFLD." (PMID 24905748, 2014). "The negative effect of Foxa1 on DGAT2 is of particular relevance as knocking down DGAT2 protects against fat-induced hepatic steatosis and insulin resistance." (PMID 22238690, 2012). "DGAT catalyses the committed step in triacylglycerol synthesis with DGAT2 being the dominant DGAT enzyme controlling triacylglycerol homeostasis in vivo, and PNPLA3 has been implicated in the development of hepatic steatosis." (PMID 22974251, 2012).
Hepatic steatosis (continued). "Conversely, the chronic suppression of DGAT2 expression using a DGAT2-specific antisense oligonucleotide (ASO) has been associated with increased levels of ALT, a marker of hepatic inflammation, in mice with diet-induced hepatic steatosis." (PMID 39456242, 2024). "Additionally, another ACC1/2 inhibitor PF-05221304, either alone or in combination with a DGAT2 (diacylglycerol O-acyltransferase 2) inhibitor, significantly reduces hepatic steatosis in patients with MASLD." (PMID 39403635, 2024). "Suppression of diacylglycerol acyltransferase-2 (DGAT2), but not DGAT1, with antisense oligonucleotides reversed diet-induced hepatic steatosis and insulin resistance, suggesting that PNPLA3-mediated lipid accumulation is possibly associated with DGAT2 signaling." (PMID 39000384, 2024). "Thus, it suggests that the elevated CD36 and DGAT2 levels contribute to VPA-induced liver steatosis, which is further supported by the improved lipid deposit and the decreased CD36/ DGAT2 levels after probiotics treatment." (PMID 37971986, 2023). "KDM7A overexpression could erase the H3K9me2 and H3K27me2 repressive markers on the DGAT2 promoter, thereby increasing the expression of DGAT2 and TG accumulation, which, finally, induced hepatic steatosis." (PMID 37834101, 2023). "In addition, VPA treatment caused liver steatosis accompanied with the upregulation of CD36 and DGAT2." (PMID 37971986, 2023). "However, under hepatic steatosis states such as obesity, KDM7A is overexpressed and erases repressive H3K9me2 and H3K27me2 on the promoter of DGAT2, which leads to increased TG accumulation and results in hepatic steatosis." (PMID 34681759, 2021). "Several reports have demonstrated that DGAT2 contributes to the development of hepatic steatosis." (PMID 34681759, 2021). "Furthermore, the contradictory role of DGAT2 during hepatic steatosis progression to NASH has been reported." (PMID 34681759, 2021). "Additionally, adenovirus-mediated overexpression of KDM7A in mice resulted in hepatic steatosis, which was accompanied by increased expression of hepatic DGAT2." (PMID 34681759, 2021). "Therefore, the in vivo data show that KDM7A is an epigenetic regulator involved in the development of hepatic steatosis through the upregulation of DGAT2 expression." (PMID 34681759, 2021). "In the present study, we investigated whether KDM7A plays a role in the development of hepatic steatosis through the upregulation of DGAT2 in vitro and in vivo." (PMID 34681759, 2021). "To determine whether the expression of KDM7A and DGAT2 correlates with hepatic steatosis pathogenesis, we examined the expression of KDM7A and DGAT2 in hepatic steosis-induced cell and animal models." (PMID 34681759, 2021). "We observed the mRNA level of DGAT2, which encodes an enzyme that catalyzes the final step in TAG synthesis, was significantly decreased by compound C3 treatment in a dose-dependent manner by 46% under condition of hepatic steatosis." (PMID 33334026, 2020). "Thus, oleic acid-induced lipid accumulation and DGAT2 expression are modified by BMP signaling in this in vitro model of hepatic steatosis." (PMID 32561790, 2020). "Thus, treatment of db/db mice with a small molecule inhibitor of BMP signaling reduced hepatic steatosis and Dgat2 mRNA in a dose-dependent fashion." (PMID 32561790, 2020). "In particular, recent observations demonstrated that DGAT2 catalyzes the de novo synthesis of triacylglycerols, giving to this enzyme a pivotal role in the development of carbohydrate-induced hypertriglyceridaemia and, consequently, hepatic steatosis." (PMID 31311123, 2019). "However, suppression of DGAT2 pharmacologically in the liver has been proved to reverse hepatic steatosis, insulin resistance, and hypertriglyceridaemia." (PMID 31019978, 2019). "Increased gene expression of DGAT2 has been reported to promote hepatic steatosis." (PMID 30513881, 2018).
Hepatic steatosis (continued). "Promoting fatty acid esterification by diacylglycerol O-acyl transferase-2 (DGAT2) stimulates hepatic triglyceride synthesis that can contribute to hepatic steatosis and production of triglyceride-rich very low density lipoproteins (VLDLs), which characterizes NAFLD." (PMID 30513881, 2018). "In addition, Dgat2 ASO treatment in rats with diet-induced hepatic steatosis was shown to reduce hepatic diacylglycerol and TG contents, but Dgat1 ASO treatment did not reduce either." (PMID 27266874, 2016). "For example, overexpression of diacylglycerol acyltransferase 2 (DGAT2) which catalyzes the final step in triacylglycerol (TG) biosynthesis in the liver increases hepatic steatosis, manifested as increased amounts of hepatic TG, diacylglycerol, ceramides, and unsaturated long-chain fatty acyl-CoAs." (PMID 26893932, 2015). "These drugs act on various metabolic targets, including LXRα, ACC, diacylglycerol O-acyltransferase 2 (DGAT2), FASN, FXR, and fibroblast growth factors (FGFs), to regulate lipid synthesis, breakdown, and transport, thereby improving metabolic abnormalities associated with fatty liver disease." (PMID 39858534, 2025). "Combined with previous research reavealing that oxidative stress is responsiple for the upregulation of CD36 and DGAT2, it is considered that probiotics could provide a certain degree of protection against VPA-caused liver steatosis through the alleviation of oxidative stress." (PMID 37971986, 2023). "However, SR treatment attenuated HFD-induced hepatic steatosis by suppressing TG contents and the expression of fatty acid transport- and lipogenesis-related genes including Fabp1, Fabp4, Slc27a5, Pparg, Mlxipl, Srebf1, Srebf2, Fas, Dgat1, and Dgat2." (PMID 35454963, 2022). "Accordingly, we hypothesized that KDM7A epigenetically upregulates DGAT2 expression by erasing the transcriptionally repressive histone marks H3K9me2 and H3K27me2 on the promoter of DGAT2, eventually leading to hepatic steatosis through increasing TG synthesis." (PMID 34681759, 2021). "Therefore, we believe that DGAT2 may be a potential downstream target gene of KDM7A necessary for the development of hepatic steatosis." (PMID 34681759, 2021). "In addition to inhibition of SGLT2, the improvement in hepatic steatosis and lipid synthesis may be mediated via up-regulation of PPARα1 and down-regulation of DGAT2, PPARγ1 and PPARγ2." (PMID 28665967, 2017). "Mice overexpressing DGAT2 did not have abnormalities of glucose tolerance or insulin levels, supporting the notion that hepatic steatosis may not necessarily be caused by insulin resistance." (PMID 26893932, 2015). "As insulin resistance is the key marker for NASH, the DGAT2 gene polymorphism might only be associated with non-progressive fatty liver." (PMID 24786095, 2014). "Since insulin resistance is the key marker for NASH, the DGAT2 gene polymorphism might only be associated with non-progressive fatty liver." (PMID 24132155, 2013). "Since accumulation of excess TGs can lead to the pathogenesis of multiple metabolic disorders, such as obesity, type II diabetes, and fatty liver disease, DGAT1 and DGAT2 have been considered potential targets for the treatment of metabolic diseases." (PMID 38500157, 2024). "In line with this assumption, hepatic overexpression of DGAT2 markedly increased DAG levels in the liver of the transgenic mice and knockdown of MGAT1 expression protected mice from HFD and PPARg-induced hepatic steatosis, respectively." (PMID 37059417, 2023). "TMP alleviated hepatic steatosis (lipid contents and lipid droplets) in high-fat-fed mice and down-regulated the PPARγ, CD36, and DGAT2 gene levels." (PMID 33807173, 2021). "The DHA-rich diet reduced liver steatosis in DIO mice, decreasing lipogenic genes (Dgat2, Scd1, Srebp1c), and upregulated lipid catabolism genes (Hsl/Acox) expression." (PMID 33546405, 2021).